CYP2C19 (cytochrome P450 family 2 subfamily C member 19)
Diseases named in the same sentence as CYP2C19 in open-access papers (continued):
Sharing a sentence is not in itself a finding about the gene and the disease.
Peptic ulcer (10 papers, 2013 to 2025). The term peptic ulcer refers to acid peptic injury of the digestive tract, resulting in mucosal break reaching the submucosa. "Thus, PPI metabolism is influenced by CYP2C19 polymorphisms, which influence treatment outcomes in patients with peptic ulcer disease." (PMID 41249771, 2025). "The distribution of CYP2C19 genotypes varies among patients with gastrointestinal disease, and rapid metabolizer genotypes may increase susceptibility to peptic ulcer disease and gastrointestinal bleeding." (PMID 41249771, 2025). "Polymorphisms in CYP2C19 are associated with peptic ulcer disease." (PMID 41249771, 2025). "In our recent reports, the genotypes of CYP2C19 could be modified by the donor graft not only on the drug metabolism for the peptic ulcer, but also possible on the immunosuppression agent causing abnormal liver function at the first month after LDLT." (PMID 25975271, 2015). "CYP2C19 may also influence arachidonic acid metabolism predisposing to peptic ulcer disease and vascular disease." (PMID 24690327, 2014). "Consequently, we performed genetic testing of CYP2C19 genotype in order to determine whether this influenced long-term efficacy of esomeprazole for prevention of peptic ulcers in our at-risk Japanese population." (PMID 23530709, 2013). "Our research showed that the frequencies of CYP2C19 EM, IM, and PM phenotypes in pediatric patients infected with H. pylori with gastritis and peptic ulcer were 40.1%, 46.4%, and 13.5%, respectively." (PMID 39030549, 2024). "In liver transplant recipients with the PM CYP2C19 genotype, lower doses of proton-pump inhibitors can be used to avoid drug intoxication in the treatment of peptic ulcer disease." (PMID 25975271, 2015). "While CYP2C19 has a minor role in NSAID metabolism, it has been associated with peptic ulcer disease, particularly with the CYP2C19*17 variant, adding complexity and heightening the risk of gastrointestinal side effects, especially in PM patients exposed to NSAIDs for postoperative pain management." (PMID 38672085, 2024). "Therefore, we conducted this study to determine the impact of CYP2C19 and MDR1 C3435T polymorphisms on the outcome of eradication therapy in Vietnamese children with gastritis and peptic ulcers to optimize the effectiveness of H. pylori eradication therapy in children." (PMID 39030549, 2024). "The distribution of CYP2C19 EM, IM, and PM phenotype in the gastritis group was not significantly different from the peptic ulcer patient group (p > 0.05)." (PMID 39030549, 2024). "The eradication rate of standard triple therapy was affected by the history of smoking (P = 0.033), presence of peptic ulcer (P = 0.002), and clarithromycin resistance (P < 0.001), but not by host CYP2C19 genotype and other clinical factors." (PMID 26632893, 2015). "A non-randomized trial showed that CYP2C19 genotype might affect the efficacy of H. pylori eradication in peptic ulcer patients treated with pantoprazole." (PMID 23646118, 2013). "A recent study showed that the CYP2C19 genotype, unlike MDR1 and IL-1B genotypes, had an impact on the efficacy of Helicobacter pylori eradication in peptic ulcer patients treated with pantoprazole in triple therapy administrations." (PMID 23617933, 2013).
dyslipidemia (9 papers, 2014 to 2026). "The results showed that metabolic syndrome was correlated with higher levels of clozapine and CYP2C19*2 and leptin receptor G alleles." (PMID 33187329, 2020). "After adjusted for dyslipidemia and concomitant use of statins and proton pump inhibitors, our results showed that patients with CYP2C19*2/*2 genotype showed significantly increased risk of CR (OR 7.406, 95% CI 0.894–61.361; P = 0.063) as compared with CYP2C19*1/*1homozygotes." (PMID 36581799, 2022).
mental disorder (9 papers, 2014 to 2025). A disease that has its basis in the disruption of mental process. "In conclusion, this study represents the first large-scale evaluation of clinically actionable CYP2D6 and CYP2C19 variants in a Central Indian population with common mental disorders." (PMID 41378208, 2025). "This study presents the first comprehensive analysis of the prevalence and clinical relevance of clinically actionable CYP2D6 and CYP2C19 alleles, genotypes, and predicted metabolizer phenotypes in a Central Indian population of 509 individuals diagnosed with common mental disorders." (PMID 41378208, 2025). "Besides its relation to drug tolerance (adverse drug reactions), CYP2C19 polymorphisms are also studied in regard to their potential role in interindividual susceptibility to psychiatric disorders." (PMID 35887684, 2022). "Genetic analyses evaluated the association between CYP2C19 variation and self-reported response, while polygenic score (PGS) analysis assessed whether genetic predisposition to psychiatric disorders and antidepressant response predicted self-reported SSRI outcomes." (PMID 40071563, 2025). "Additionally, this process can be complicated by genetic variations (e.g., CYP2C19 and CYP3A4) alternating the metabolism of SSRIs and comorbid psychiatric disorders contributing to sexual dysfunction." (PMID 38263040, 2024). "Of the 39 PGx drugs, nine drugs (23%) with more than one actionable DGI,including genes coding forCYP2D6, CYP2C19, HLA-A, HLA-B, CYP2C9, CYP4F2or VKORC1 were used by 3.9% of the PGx drug users of the population and9.7% of the PGx drug users of the combined mental disorders casecohorts." (PMID 34753194, 2022). "Despite the discordance, both the wider literature and our study showed that approximately 73%–85% of patients with mental disorders carry non-NM phenotypes in CYP2D6 and/or CYP2C19." (PMID 36895946, 2023).
schizophrenia (9 papers, 2019 to 2025). A major psychotic disorder characterized by abnormalities in the perception or expression of reality. "For example, a recent study has shown that CYP2C19 polymorphisms influenced clozapine responses during the treatment of schizophrenia." (PMID 36980961, 2023). "In conclusion, we demonstrate for the first time that higher schizophrenia-PRS and CYP2C19 predicted activity are independently associated with low symptom severity among clozapine-treated schizophrenia patients." (PMID 35393395, 2022). "In this study, the mean serum C/D ratios of valproic acid increased in accordance with the number of the mutated alleles for CYP2C19 in schizophrenia patients." (PMID 34848811, 2021). "As for, that the effect of CYP2C19 polymorphism on serum concentration of VPA in schizophrenia patients treated with other antipsychotic drugs combined with VPA remains to be further observed." (PMID 34848811, 2021). "Therefore, we investigate the effects of CYP2C19 polymorphisms on the steady-state serum concentrations of valproic acid in Chinese Han patients with schizophrenia, which might be useful for VPA dose adjustment in clinical practice." (PMID 34848811, 2021). "We show that high schizophrenia-PRS and genotype-predicted CYP2C19 enzyme activity are independently associated with lower symptom severity among individuals treated with clozapine." (PMID 35393395, 2022). "Using a novel approach of integrating genome-wide, PRS, and CYP analyses, we demonstrate that higher schizophrenia-PRS and higher genotype-predicted CYP2C19 enzyme activity are independently associated with lower symptom severity while on clozapine." (PMID 35393395, 2022). "Analyses were based on previously unpublished data from an RCT investigating the clinical utility of routine genotyping of CYP2D6 and CYP2C19 in patients with schizophrenia." (PMID 36294867, 2022). "In a recently published randomized controlled trial (RCT), we investigated the clinical utility of routine genotyping of CYP2D6 and CYP2C19 in patients with schizophrenia." (PMID 36294867, 2022). "The determination of the CYP2C19 genotypes may be useful for dosing adjustment in schizophrenia patients on valproic acid therapy." (PMID 34848811, 2021). "We investigated the effects of age, sex, and genetic polymorphisms in CYP isoforms (CYP1A2, CYP2B6, CYP2C19, CYP2D6, and CYP3A5) and drug transporters (ABCG2 and SLCO1B1) on the plasma concentrations of clozapine, N‐desmethylclozapine, and clozapine N‐oxide in Japanese patients with schizophrenia." (PMID 40740505, 2025). "As the prevalence of cigarette smoking is high in schizophrenia patients (around 70%–80%) and probably even higher in treatment-resistant schizophrenia patients, we believe that the DDI observed in our study between PPIs and clozapine is probably more linked to the CYP2C19 inhibition by PPIs." (PMID 37849735, 2023). "DNA was isolated from the peripheral blood samples of 27 patients with schizophrenia receiving clozapine maintenance treatment, and the pharmacokinetics‐related genes (CYP1A2, CYP2B6, CYP2C19, CYP2D6, CYP3A5, ABCG2, and SLCO1B1) were genotyped." (PMID 40740505, 2025).
chronic kidney disease (8 papers, 2017 to 2025). Impairment of the renal function secondary to chronic kidney damage persisting for three or more months. "Poor CYP expression was expected in leukocytes of patients with end-stage renal disease; however, the expression of CYP1A2, CYP2C9, CYP2C19 and CYP3A4 was efficiently quantified using the refined method." (PMID 32638224, 2020). "The expression of CYP1A2, CYP2C9, CYP2C19 and CYP3A4 was determined in leukocytes of 105 patients with end-stage renal disease and 110 healthy organ donors." (PMID 32638224, 2020). "Second, although direct evidence has previously been provided for the correlation between leukocyte expression and hepatic enzyme activities (as well as hepatic expression) of CYP1A2, CYP2C9, CYP2C19 and CYP3A4, it should be validated for patients with end-stage renal disease." (PMID 32638224, 2020). "Comparing organ donors and the patients with end-stage renal disease, significant differences were observed in the proportion of subjects expressed CYP mRNA at low, normal and high levels (Chi2 for CYP1A2: 40.2, for CYP2C9: 87.9, for CYP2C19: 47.2, for CYP3A4: 29.9; df = 2, p < 0.0001)." (PMID 32638224, 2020).
hepatocellular carcinoma (8 papers, 2013 to 2023). A malignant tumor that arises from hepatocytes. "For example, CYP2C9, CYP2C19, and CYP3A4, which are mainly located in the liver, are diagnostic markers of hepatocellular carcinoma." (PMID 37629205, 2023). "We found that CYP2C19 PM genotype, in stratified analysis by cancer type, was statistically related with elevated risks for gastric cancer, esophagus cancer and hepatocellular carcinoma." (PMID 23874401, 2013). "Promoter hyper-methylation has been reported to result in repression of CAR expression, which induced the down-regulation of the CYP2C19 gene, in human non-cancerous liver and human hepatoma cell lines." (PMID 29774122, 2018).
angina (7 papers, 2015 to 2023). "Recurrent angina, AMI, and intra-stent thrombosis occurred less often in CYP2C19 681 GG patients than CYP2C19 681A allele (GA+AA) patients (2/59 vs. 8/51, 1/59 vs. 6/51, 0 vs. 4/51, respectively, p < 0.05)." (PMID 26147597, 2015). "All these studies highlighted the crucial rule of CYP2C19 LOF alleles in Southeast Asians with AMI, but not in patients with stable angina undergoing elective PCI." (PMID 36072879, 2022). "Other studies from East Asia also indicated increased MACE events in CYP2C19 PM in the setting of AMI but not in the setting of stable angina." (PMID 36072879, 2022). "Even the association of CYP2C19 polymorphisms with platelet responsiveness to Clopidogrel was largely approved among ACS/PCI patients, the association among patients under Clopidogrel for other indications (e.g. stable angina and arterial fibrillation), have been declared negative." (PMID 29347970, 2018).
COVID-19 (7 papers, 2022 to 2025). A disease caused by infection with severe acute respiratory syndrome coronavirus 2. "The risks of COVID-19 severity and COVID-19 mortality were higher among CYP2C19 likely intermediate, intermediate and poor metabolizers." (PMID 39012339, 2024). "Additionally, it was shown that COVID-19 severity was associated with significant differential gene expression for several genes involved in drug-metabolizing enzymes and membrane transporters, including upregulation in CYP2C9 and CYP2C19." (PMID 39767601, 2024). "CYP1A2, CYP2D6, and CYP2C19 metabolize fluvoxamine and its therapeutic concentrations could be significantly impacted by varying miR-155 levels, which differ between young, healthy individuals and older individuals with co-morbidities in COVID-19." (PMID 38862591, 2024).
liver failure (7 papers, 2017 to 2024). A liver disease characterized by the liver losing or has lost all of its function. "Additionally, a comprehensive summary and analysis of existing studies’ recommendations on VRZ dose adjustments based on CYP2C19 genetic polymorphisms and hepatic insufficiency are provided, offering a more comprehensive reference for dose selection and adjustments of VRZ in this patient population." (PMID 37693307, 2023). "When making dosage adjustments, special attention should be given to the impact of CYP2C19 gene phenotype in hepatic insufficiency patients on VRZ dosage adjustments." (PMID 37693307, 2023). "The consideration of CYP2C19 genotyping before VCZ treatment may be helpful in the management of high-risk populations, such as patients with hepatic insufficiency or those receiving medications that may increase the risk of VCZ toxicity by drug-drug interactions (e.g., proton- pump inhibitors)." (PMID 33834148, 2020). "The reported pharmacokinetic study suggested that CYP2E1 was the most stable enzyme, whereas CYP2C19 (with CYP1A1 and CYP2D6 in the middle) was the most vulnerable in liver failure." (PMID 34575411, 2021). "The published clinical pharmacokinetic studies suggest that liver failure can affect CYP1A2, CYP2C19, CYP2D6, CYP2E1 and CYP3A4 activities." (PMID 34575411, 2021). "Additionally, the impact of CYP2C19, CYP3A4, and CYP2C9 genes on hepatic insufficiency patients with IFI should be carefully considered." (PMID 37693307, 2023). "Our findings are contradictory to our hypothesis that liver failure would reduce the predominant metabolism of voriconazole by the cytochrome P450 enzymes (CYP), mainly CYP2C19 as well as CYP3A4 and CYP2C9." (PMID 34683408, 2021). "Therefore, it is crucial to focus on the impact of CYP2C19, CYP3A4, and CYP2C9 gene phenotypes in hepatic insufficiency patients on VRZ plasma concentrations, as this holds positive implications for the successful treatment of hepatic insufficiency with concomitant invasive fungal infections." (PMID 37693307, 2023).
gastric cancer (6 papers, 2013 to 2022). A primary or metastatic malignant neoplasm involving the stomach. "The risk of gastric cancer (aHR 2.47) in the CYP2C19 non‐extensive metabolizers, that is, the intermediate and poor metabolizers, was elevated compared with that in extensive metabolizers; however, this difference was not statistically significant." (PMID 34263071, 2021). "In addition, COX2 inhibitors showed relatively higher chemopreventive effects, and we identified CYP2C19 poor metabolizers as a potential high‐risk population for post‐eradication gastric cancer." (PMID 34263071, 2021). "Furthermore, we evaluated the association between gastric cancer and patients' genotype of CYP2C19, which is involved in PPI metabolism." (PMID 34263071, 2021). "We found that CYP2C19 non‐extensive metabolizers who use PPIs are at high risk of gastric cancer." (PMID 34263071, 2021).
lung carcinoma (6 papers, 2013 to 2022). "Thus, the clinical application of anlotinib should be based on the genotyping of CYP450 in lung cancer, particularly for rs3814637 and rs11568732 of CYP2C19." (PMID 35814206, 2022). "Genetic polymorphisms of CYP2C19 were found to be associated with a greater risk of HCC in Japanese cirrhotic patients with HCV infection 43, as well as a significant risk of triple‐negative breast cancer 44 and lung cancer in combination analysis with smoking in a Chinese population." (PMID 29479826, 2018).
cerebrovascular diseases (5 papers, 2022 to 2024). "In previous reports, CYP2C19*2 is also determined as a risk factor gene associated with recurrent vascular events in cardiovascular and cerebrovascular diseases; however, the underlying mechanism is unclear." (PMID 37342754, 2023). "Moreover, CYP2C19 gene polymorphism is also associated with some other cardiovascular and cerebrovascular diseases." (PMID 37024851, 2023). "Cytochrome P450 2C19 (CYP2C19) plays an vital role in the course of cardiovascular and cerebrovascular diseases by affecting lipid metabolism." (PMID 39472784, 2024). "Populations varied: the studies of Genomadix (Spartan) CYP2C19 tests mainly recruited patients undergoing PCI, the GMEX System study recruited healthy people and people with cardiovascular and cerebrovascular diseases and the Genedrive study tested donor specimens." (PMID 39229818, 2024). "The study of the Genedrive CYP2C19 ID Kit recruited donor specimens (no further information provided), and the GMEX system study recruited healthy people and people with cardiovascular and cerebrovascular diseases." (PMID 39229818, 2024).
endometriosis (5 papers, 2012 to 2024). The growth of functional endometrial tissue in anatomic sites outside the uterine body. "Certain CYP2C19 polymorphisms associated with increased CYP2C19 activity confer a decrease in estrogen levels, potentially reducing the risk of endometriosis and vice versa." (PMID 39062866, 2024). "Instead, CYP2C19 (Cytochrome P450 Family 2 Subfamily C Member 19), a nearby gene, was found to be weakly associated with endometriosis." (PMID 34502183, 2021). "The authors proposed that variants of CYP2C19 may contribute to endometriosis susceptibility in both familial and sporadic cases." (PMID 35514537, 2022). "The authors concluded that there are potential high-penetrance susceptibility loci on chromosomes 7p13–15, 10q26, and 20p13, and genes such as CYP2C19, INHBA, SFRP4, and HOXA10, which are probably responsible for the risk of development of endometriosis." (PMID 32370117, 2020). "CYP2C19 is a plausible candidate for endometriosis because it is involved in the metabolism of drugs and E including conversion of E2 to estrone (E1), and the production of E1 and E2 2a- and 16a-hydroxylation metabolites." (PMID 22924156, 2012). "Future studies should follow up by investigating novel rare genetic variants in this region and conducting gene expression analyses to further understand the role of CYP2C19 in endometriosis." (PMID 22924156, 2012). "Whilst there is no specific evidence for a role for CYP2C19 in endometrium or endometriosis, it is notable that expoxygenase activity has been studied in the context of macrophage activity in wounding and fibrosis both processes relevant to development of endometriosis lesions." (PMID 35514537, 2022).
fungal infections (5 papers, 2017 to 2024). "In this study, we investigated the association of SNPs in CYP2C19, CYP3A4, ABCB1, and FMO3 and the plasma concentrations of voriconazole in Thai patients with invasive fungal infections." (PMID 33124772, 2020). "We observed four Caucasian patients who underwent allogenic hematopoietic stem cell transplantation, treated with voriconazole for prevention of fungal infections, to establish the impact of CYP2C19*2/*17 genotype on side effect occurrence." (PMID 28247033, 2017).
gastritis (5 papers, 2013 to 2024). Inflammation of the stomach. "Patients demonstrating the CYP2C19*1/*17 genotype suffered mainly from skin (rash, erythema), nervous system (headache, vertigo), and gastrointestinal disorders (nausea, gastritis)." (PMID 28685218, 2018). "In addition, PTGS2, TRL4, MMP9, JAK1, EGFR, CYP2C19, and PTGS1 were identified as crucial anti-gastritis target genes in C. cassia." (PMID 35336597, 2022).